CTLA4 (cytotoxic T-lymphocyte associated protein 4)
Diseases named in the same sentence as CTLA4 in open-access papers (continued):
Sharing a sentence is not in itself a finding about the gene and the disease.
tumor (continued). "Following PDL1 blockade alone or combined PDL1 and CTLA4 blockade T cell motility was decreased in all regions of the tumor and overall infiltration was increased, consistent with increased cognate interactions in the tumor environment." (PMID 33968757, 2021). "Immune checkpoints such as PD-L1/CD274 and CTLA4 are often overexpressed in tumor cells to devitalize effector T cells and suppress immune responses, which could be targets for immunotherapy." (PMID 33928021, 2021). "TIGIT expression, but not PD-1 or CTLA-4, was found to be upregulated on exhausted NK cells and was associated with tumor progression in severe combined immunodeficient mice." (PMID 33946954, 2021). "CTLA-4-targeting immunotherapy significantly depletes tumor infiltrating Tregs, but it also may induce severe immunotherapy-related adverse events." (PMID 34806028, 2021). "This anti-tumor immunity is negatively regulated by CTLA-4 molecules." (PMID 34541363, 2021). "Curcumin can improve tumor immunotherapy targeting PD-1/PD-L1 and CTLA-4." (PMID 34094974, 2021). "Even after treatment with checkpoint blockade immunotherapies (CBI), including antibodies for cytotoxic T-lymphocyte associated protein 4 (CTLA-4) and programmed-cell-death protein 1 (PD-1), most patients presented insufficient systemic immune responses for tumor regression." (PMID 33420008, 2021). "Radiation therapy can also affect the up-regulation of PD-1 and CTLA-4 molecules on tumor cells." (PMID 34587185, 2021). "The anti-tumor effects of anti-CTLA-4 mAb were significantly compromised in these two groups but could be re-established following colonization with B. fragilis." (PMID 34305883, 2021). "Treatment of mice bearing poorly immunogenic B16 tumors with co-administration of S100, anti-PD-1, and anti-CTLA-4 yielded significant increases in IFN-γ-secreting tumor-specific T cells and conferred a significant survival benefit over mice receiving single-agent regimens." (PMID 33995422, 2021). "Anti-CTLA-4-antibodies can induce long-lasting tumor remissions." (PMID 33196890, 2021). "Importantly, CELF2 was significantly associated with plenty of immune checkpoint molecules (ICMs) and outperformed five prevalent biomarkers including PD‐1, PD‐L1, CTLA‐4, CD8 and tumour mutation burden in predicting immunotherapeutic responses." (PMID 34288370, 2021). "Indeed, previous studies have confirmed that immunotherapy using immune checkpoint blockade, such as anti-PD-1 and anti-CTLA-4, to induce amplified endogenous anti-tumor T cell responses, has changed the clinical outcomes of ccRCC patients." (PMID 34567061, 2021). "However, upregulation of PD-L1 on tumor cells rendered the majority of tumor-bearing mice resistant to RT+anti-CTLA-4, and additional blocking of PD-1/PD-L1 (triple-therapy) significantly improved the overall efficacy." (PMID 34830176, 2021). "Central memory (Tcm) and effector memory (Tem) CD4pos and CD8pos T cells displayed reduced levels of T cell exhaustion and inhibitory markers such as LAG3, CTLA4 and PD-1, consistent with improved function of memory CD4pos and CD8pos T cell populations in Osm−/− tumours." (PMID 34921158, 2021). "The anti-tumor activity of the anti-CTLA-4 blockade was originally hypothesized to depend on the reinvigoration of dysfunctional CTLA-4-expressing Tconv cells." (PMID 34868991, 2021). "In addition, studies have shown that CD8 + T cells can increase the sensitivity of tumor cells to radiotherapy and PD-L1/PD-1 or CTLA-4 blocking therapy by promoting ferroptosis." (PMID 34316400, 2021). "In addition, the combination treatment of another CCR4 antagonist piperidinyl-azetidines and immune checkpoint inhibitors, such as anti-PD-L1 and CTLA-4 antibodies, efficiently augmented tumor-specific immune responses." (PMID 34885241, 2021).
tumor (continued). "A study has shown that the ureido-sulfonamide CAIX inhibitor SLC-0111 in combination with anti-PD-1 and anti-CTLA4 increased the effector function of T-cells (granzyme B production), inhibited tumour growth, and reduced metastasis in the B16.F10 and 4T1 syngeneic tumour models." (PMID 33923305, 2021). "While neither therapy alone yielded any increases in overall survival, the combination of both SWCNT-ANXA5 enhanced photothermal therapy and anti-CTLA-4 checkpoint inhibition improved overall survival, leading to 55% survival at 100 days post-tumor inoculation." (PMID 33411055, 2021). "Importantly, CTLA-4 (cytotoxic T lymphocyte antigen 4) suppresses activation of cytotoxic T cells, thereby contributing to the evasion of anti-tumor immune responses." (PMID 33420250, 2021). "Interestingly, in 4T1 mammary cancer models, anti-CTLA4 treatment increased motility of T cells in the tumor." (PMID 33968757, 2021). "A novel smart agent is engineered by coating a tumor microenvironment responsive ZIF‐8 on the novel recombinant humanized PD‐L1/CTLA‐4 bispecific single‐domain antibody‐Fc fusion protein to overcome the higher costs and greater side effects of single‐agent immunotherapies." (PMID 34473430, 2021). "In the NICHE study assessing dual agent inhibitory checkpoint blockade (PD-1 and CTLA-4), tumour regression was observed in 100% of MSI tumours, with a major pathological response (MPR ≤ 10% residual viable tumour) rate of 95% and a pathological complete response (pCR) rate of 60%." (PMID 34302062, 2021). "Finally, MDSC confers resistance to immune checkpoint inhibitors, as MDSC depletion was shown to enhance the efficacy of anti-PD1 and anti-CTLA4 treatment with a complete tumor regression and a decrease of metastasis in an aggressive breast tumor mouse model." (PMID 33418996, 2021). "Paradoxically, anti-PD-L1 administered as a single therapy may enhance CTLA-4/CD80-mediated immunosuppression in some patients due to the disruption of the tumor-suppressive CD80 and PD-L1 in cis interaction." (PMID 33923750, 2021). "However, the composition of tumor infiltrating immune cells in these tumors was modified when BEMPEG or anti-CTLA-4 were added to local treatments." (PMID 33937052, 2021). "Similarly, an immune-active tumor microenvironment was reported to mediate the antitumor activity of CTLA-4 blockade." (PMID 33926465, 2021). "Moreover, several immunosuppressive proteins including PD-1, PD-L1, and CTLA-4 were found to be enriched in hypoxic sEVs, contributing to hypoxia-dependent modulation of anti-tumor immune responses." (PMID 34439329, 2021). "Anti-CTLA-4 pathway blockade mediates selective depletion of CTLA-4+ tumor-infiltrating Tregs and could therefore indirectly rescue NK cells from Treg suppression." (PMID 33995422, 2021). "In all cases of TGFβ inhibition, anti-CTLA-4 therapy was superior at controlling tumor growth." (PMID 34789823, 2021). "In this review, we discuss the advances that have been made in generating immunotherapeutic alternatives to CTLA-4 and PD-1/PD-L1 in experimental model systems of solid tumours, as well as highlighting the challenges in treating secondary tumours with immunotherapy." (PMID 33262520, 2021). "Indeed, HBI-8000 combined with any of the 3 ICIs tested (PD-1 Ab, PD-L1 Ab, and CTLA-4 Ab) displayed enhanced tumor growth inhibition." (PMID 34461854, 2021). "However, the addition of a PD-1 inhibitor to the anti-CTLA-4/PLGA-MP-setup supports tumor eradication efficacy and prolongs survival." (PMID 34006895, 2021). "Wu and his colleagues have shown that abnormal circadian genes contribute to T cell exhaustion and global upregulation of immune inhibitory molecules, such as programmed death-ligand 1 (PD-L1) and cytotoxic T-lymphocyte antigen (CTLA)-4, which promote tumor development." (PMID 34285836, 2021).
tumor (continued). "Notably, a strong cooperative effect between LAG-3, PD-1, and CTLA-4 has been elucidated in recent reports, highlighting the relevance of the interplay between these checkpoint molecules in the regulation of tumor immunity." (PMID 33430105, 2021). "Furthermore, Mbofung and colleagues demonstrated that ganetespib in combination with anti-CTLA4 and anti-PD-1 antibodies improved survival and anti-tumor response in mice bearing MC38/gp100 tumors." (PMID 33815422, 2021). "Consequently, inhibiting these receptors with antibodies has been shown to enhance anti-tumor T cell activity and several clinical trials are underway to evaluate the efficacy of anti-CTLA-4 and anti-PD-1 therapies in BCBMs." (PMID 34716900, 2021). "Moreover, the density of CTLA-4+ TILs was determined as an independent predictor of OS, and PD-L1 expression in tumor cells was an independent predictor of cumulative recurrence." (PMID 34526987, 2021). "Activated TLR8 pathway remarkably reshapes the tumor immune microenvironment by decreasing infiltrating myeloid-derived suppressor cells (MDSCs), regulatory T cells (Tregs), and immunosuppressive markers, such as CTLA-4." (PMID 33386920, 2021). "However, the anti-tumor effects of anti-CTLA4 treatment largely rely on the antibody-dependent cellular cytotoxicity (ADCC) mediated depletion of tumor-infiltrating Tregs." (PMID 33679808, 2021). "Here, we also demonstrate that the CTLA-4 signal was activated in tumor tissues of ICCs." (PMID 34526987, 2021). "molecules like programmed cell death protein 1 receptor/ ligand (PD-1, PD-L1) and cytotoxic T lymphocyte antigen-4 (CTLA-4) has yielded encouraging outcomes, emphasizing the essential role of the tumor microenvironment (TME) to influence the clinical therapeutic outcome." (PMID 34612148, 2021). "Therefore, using monoclonal antibody to block the expression of CTLA-4, can reduce the inhibitory activity of Tregs, and achieve tumor suppression effects." (PMID 34737750, 2021). "A subset of infiltrating lymphocytes and tumor cells highly expressed CTLA-4." (PMID 33196890, 2021). "When anti-CTLA-4 is combined with anti-4-1BB antibodies enhance it increased tumor immunity." (PMID 34267616, 2021). "This may represent a central role of CTLA-4 expression in tumour progression cycle through inducing tumour immune escape." (PMID 35047074, 2021). "Furthermore, mRNA expression studies, demonstrate a negative correlation between DVL-1 expression and the markers for T cell exhaustion (e.g. CTLA4, HAVCR2), CD8+ T cell (CD8B), tumor-associated macrophages (TAM), T helper cell, and dendritic cells." (PMID 34659647, 2021). "CTLA-4-targeting immunotherapy significantly depletes tumor infiltrating Tregs but may also induce fatal immunotherapy-related adverse events in some patients." (PMID 34806028, 2021). "Some important immune-associated genes, such as granzyme B, IFN-γ, IL-2, IL-12, FoxP3 and STING, are regulated via epigenetic mechanisms in immune or/and cancer cells, as are immune checkpoint molecules (PD-1, CTLA-4, TIM-3, LAG-3, TIGIT) expressed by immune cells and tumor-associated stromal cells." (PMID 34930302, 2021). "The tumor volumes were 2106 ± 205 mm3 on day 17 in the control group treated with vehicle only but were 23 ± 4 mm3 in the group treated with the anti-CTLA-4 antibodies on day 5, which indicated a statistically significant difference in antitumor activity between the treated and vehicle groups." (PMID 33466394, 2021). "Other receptor involved in tumor evasion mechanisms is CTLA‐4, originally described on T cells." (PMID 34323406, 2021). "In agreement with our flow cytometry results, we identified a significant upregulation in several genes encoding for immune checkpoint inhibitory molecules (e.g. Pdcd1, Lag3, Ctla4, Icos, Tigit, Tnfrsf18) in tumor-infiltrating CD4/ALK4-KO CD4+ T cells, compared to WT CD4+ T cells." (PMID 34548096, 2021).
tumor (continued). "Furthermore, co-administration of CMG017 with checkpoint inhibitors (a-PDL1 and a-CTLA-4) to tumor-challenged mice resulted in tumor regression and the establishment of memory CD8+ T cell responses." (PMID 33747948, 2021). "Furthermore they showed that in situ tumor ablation can be combined with immunomodulation via checkpoint inhibition (anti-CTLA-4) or regulatory T-cell depletion to enhance the CD8+ T-cell activation and clinical response." (PMID 34502076, 2021). "Anti-CTLA-4 could partially relieve the immunosuppressive TME with enhanced anti-tumor immunity of T lymphocytes." (PMID 34858835, 2021). "The combination with either anti-PD-L1 or anti-CTLA-4 antibody could suppress tumor growth more effectively than either agent alone, primarily through reactivation of anti-tumor immunity." (PMID 33557876, 2021). "The positive correlation of the risk score with the expression levels of PDL1 (CD274), PDCD1, and CTLA4 was found, suggesting that metabolic reprogramming genes may have a significant effect on the tumor immune microenvironment." (PMID 33413205, 2021). "Many solid tumors establish immune suppression by upregulating the expression of key immune checkpoint receptors (e.g., PD-1, CTLA4) on infiltrating T cells as well as immunosuppressive ligands (e.g., PD-L1, PD-L2, B7-H4), either on tumor cells or other cell types in the tumor microenvironment." (PMID 33807608, 2021). "The addition of anti-PD-1 or -CTLA-4 antibodies significantly inhibited tumor growth compared to combination alone or single treatments; over 90% of mice were cured, and these were protected from tumor rechallenge." (PMID 34578321, 2021). "However, the density of Tregs in the tumor increased upon anti-CTLA-4 treatment in most cancer types studied." (PMID 34777387, 2021). "In the meantime, the elevated expression of ICGs such as PDCD1, CD274, CTLA4 may also modulate tumor response to immunotherapy." (PMID 35116021, 2021). "Immune checkpoint inhibitors (ICIs) can enhance the anti-tumor immune reaction of T cells by targeting cytotoxic T lymphocyte antigen-4 (CTLA-4), and programmed cell death 1 (PD-1) or its ligand (PD-L1), and have been extensively applied for various tumors, including urothelial carcinoma." (PMID 34867321, 2021). "Notably, a group from Philadelphia performed “a triple blow for cancer” whereby combination of anti-CTLA-4 Ab and radiotherapy with anti-PD-L1 Ab have demonstrated the effectiveness in impeding tumor immune escape through distinct mechanisms." (PMID 33611641, 2021). "CTLA4-targeted NIR-PIT reduced tumour progression and prolonged survival in mouse tumour models." (PMID 34332294, 2021). "However, PD-L1 + expression in tumor cells was significantly higher (p = 0.004); CTLA-4+ TILs were also significantly higher in intT (p < 0.001) and strml (p = 0.006) assessments, respectively." (PMID 34944876, 2021). "We sought to use a CTLA4-blocking antibody to enhance the immunogenicity of the survivin vaccines, as this has been reported to help break peripheral tolerance to aberrantly expressed tumor antigens." (PMID 34944889, 2021). "Moreover, combining radiation with anti-CTLA-4 blockade has been shown not only to produce regression of the irradiated tumor, but also a response in out-of-field (abscopal effect) tumor sites, in mice as well as in some case reports." (PMID 34790123, 2021). "However, within the TME, they inhibit anti-tumor immunity through multiple mechanisms including via CTLA-4 and the production of immunosuppressive cytokines TGF-β and IL-10." (PMID 34831452, 2021). "Thus, it is clear that malignant tumours co-opt PD-1 and/or CTLA-4-mediated immune checkpoint pathways to avoid immune surveillance against tumours." (PMID 33927311, 2021).
tumor (continued). "After completion of treatment with daily IT CpG injection for 5 days with intraperitoneal injections (IP) of anti-OX40/CD134 and anti-CTLA4/CD152 antibodies on days 1 and 5, total splenocytes were co-cultured in the presence of irradiated A20 tumor cells plus ant-CD28 MoAb overnight." (PMID 35008305, 2021). "Increased CTLA-4 expression results in a net inhibitory response to the T cell itself, leading to decreased T-cell survival, decreased local cytokine release (namely IL-2), and a more “pro-tumor” microenvironment." (PMID 33918476, 2021). "However, measuring the CTLA-4 levels using patient biopsies has revealed high variability even between different areas of the same tumor, as well as between primary and secondary lesions." (PMID 33925941, 2021). "The density of FOXP3+ TILs (TILsFOXP3) in ICC tumor samples was 15.7 ± 14.8/field, which is significantly higher than that in para-tumor liver tissues (4.8 ± 5.3/field, P <.001) and lower than CTLA-4 (P <.001)." (PMID 34526987, 2021). "In addition to its chemosensitizing effects, AMD3100 synergistically interacts with antibodies targeting PD‐L1 and CTLA‐4 results in enhanced T‐cell infiltration into tumor tissues, yielding a greater anticancer response." (PMID 33463063, 2021). "Anti-CTLA-4 therapy primarily interferes with the feedback mechanism to improve the proliferation and activation of more T cells, while anti-PD-1 treatment is assumed to attenuate the tumour-induced immunosuppression." (PMID 35069558, 2021). "In addition, localised treatment with oncolytic Newcastle disease virus can induce tumour infiltration with NK cells and T cells into distant tumours and sensitise distant tumours to systemic checkpoint blockade (anti-CTLA-4) therapy." (PMID 34888493, 2021). "When the CTLA-4 and PD-1 are blocked, the stimulation signal of T cells are activated, the number of cytotoxic T cells with anti-tumor activity increase, the production and proliferation of pro-inflammatory cytokines can also be promoted, and finally, the tumor destruction can be accelerated." (PMID 34090476, 2021). "Furthermore, a phase I clinical trial revealed major tumor regression in a group of metastatic melanoma patients treated with radiotherapy and an anti-CTLA-4 antibody." (PMID 33888558, 2021). "Indeed, the VISTA/CTLA-4 dual blockade has substantially inhibited tumor growth in squamous cell carcinoma." (PMID 34093577, 2021). "Moreover, an enhancement in the CD8+ cells and CD8+/Treg ratio in tumor-infiltrated lymphocytes was observed in mice receiving the anti-CTLA-4 encapsulated in nanocarriers." (PMID 33800368, 2021). "For example, ipilimumab is the first immune checkpoint blocker approved by the Food and Drug Administration and has been thought to work through inhibiting CTLA-4 on effector T cells as well as on Treg cells by depleting Treg cells in the tumor microenvironment." (PMID 34599187, 2021). "CTLA-4 blockade aims to induce robust activation of tumor reactive T cells." (PMID 33406696, 2021). "Similarly, addition of high doses of VitC to CTLA-4 and/or PD-1/PD-L1 blockade delayed tumor growth and led to pronounced tumor regression in different tumor mouse models." (PMID 34899716, 2021). "Many immune checkpoints are initiated by ligand-receptor interactions, and the receptors involved in such interactions include cytotoxic T lymphocyte-associated protein-4 (CTLA4), the PD1 receptor expressed in activated T cells, and the PDL1 and PDL2 receptors expressed on immune and tumor cells." (PMID 34490047, 2021). "The improved T cell-stimulatory capacity of λ-MYC TIDCs detected in vitro, which was also seen in an HPV16 tumor model after anti-PD1/anti-CTLA-4 treatment, may be due to the altered cytokine expression pattern, but other mechanisms cannot be precluded." (PMID 33141285, 2021).